MAN1A2P1 (mannosidase alpha class 1A member 2 pseudogene 1)
Gene: Processed pseudogene on chromosome 19 (28,790,812 to 28,792,871, reverse strand). Ensembl gene ENSG00000267799.
Diseases named in the same sentence as MAN1A2P1 in open-access papers:
MAN1A2P1 is named in the same sentence as 1 disease in open-access papers, as found by Europe PMC text mining. Sharing a sentence is not in itself a finding about the gene and the disease. The quoted sentences say what the papers report.
tumour (1 paper, 2020). "LMO1, RP11-834C11.12, MAN1A2P1, HTRA3 and ESR1 were the top five differentially hypermethylated genes in primary tumours compared to NAT." (PMID 32971738, 2020).